PARP1 (poly(ADP-ribose) polymerase 1)
Diseases named in the same sentence as PARP1 in open-access papers (continued):
Sharing a sentence is not in itself a finding about the gene and the disease.
Werner syndrome (4 papers, 2005 to 2019). "Cells from patients with Werner syndrome and Hutchinson–Guildford progeria also display defects in PARP1 activity and defective DNA repair." (PMID 31796734, 2019). "PARP1 has also been linked to aging, being present in a complex with WRN DNA repair proteins that are deficient in participants with Werner syndrome, a premature aging syndrome." (PMID 27824314, 2016). "Thus, PARP-1 polyADP-ribosylates itself and also Ku70/80, and the polyADP-ribosylated Ku 70/80 is reduced in its DNA binding affinity, and becomes attenuated in its ability to stimulate Werner syndrome (WRN) exonuclease." (PMID 16014171, 2005). "Interestingly, this module contains the PARP1 (ADPRT) gene, which directly binds to WRN to induce apoptosis upon oxidative stress induced DNA damage and is as such a prime suspect for Werner syndrome, a premature aging disease." (PMID 24119000, 2014).
acute kidney injury (3 papers, 2018 to 2023). Sudden and sustained deterioration of the kidney function characterized by decreased glomerular filtration rate, increased serum creatinine or oliguria. "The decline in PARP1 expression by nicotinamide could suppress cisplatin-induced apoptosis in renal proximal tubular cells as well as acute kidney injury in mice, which might involve the diminished induction of γ-H2AX, a reflection of DNA damage response." (PMID 37773127, 2023). "Moreover, inhibition of PARP1 degradation due to insulin-like growth factor binding protein 7 could promote the development of acute kidney injury." (PMID 37773127, 2023). "The aim of the present study is to analyze the effects of 5-aminoisoquinoline (5-AIQ), a poly(ADP-ribose) polymerase-1 (PARP1) inhibitor, over renal dysfunction and fibrosis during recovery phase of cisplatin (CisPt)-induced acute kidney injury (AKI) in rats." (PMID 29599129, 2018).
acute lung injury (3 papers, 2013 to 2025). A condition of lung damage that is characterized by bilateral pulmonary infiltrates (pulmonary edema) rich in neutrophils, and in the absence of clinical heart failure. "PARP1, as a potential target for the experimental therapy of acute lung injury (ALI), was identified over 20 years ago." (PMID 36497049, 2022). "Poly(ADP-ribose) polymerase 1 (PARP1), as a potential target for the experimental therapy of acute lung injury (ALI), was identified over 20 years ago." (PMID 36497049, 2022).
autoimmune disease (3 papers, 2020 to 2023). A disorder resulting from loss of function or tissue destruction of an organ or multiple organs, arising from humoral or cellular immune responses of the individual to their own tissue constituents. "One of the mechanisms by which oxidative stress can trigger an inflammatory response in the pathogenesis of autoimmune diseases concerns the activation of the enzyme poly (ADP-ribose) polymerase-1 (PARP-1)." (PMID 37627286, 2023). "The role of PARP-1 in the processes of DNA repair and regulation of inflammation makes the determination of its expression particularly useful in cancer and autoimmune diseases." (PMID 33572586, 2021). "PARP‐1‐mediated poly(ADP‐ribosyl)ation of FOXP3 impairs Treg function and suggests that PARP‐1 inhibitor could be potential drug for autoimmune diseases." (PMID 32644293, 2020).
B-cell neoplasm (3 papers, 2014 to 2023). A group of heterogeneous lymphoid tumors generally expressing one or more B-cell antigens or representing malignant transformations of B-lymphocytes. "In the cell lines Raji and Namalwa, used as comparative controls of other B-cell neoplasms with different PARP1 expression levels, the 72-h IC50 of AZD2461 and imatinib showed great disparity." (PMID 38067214, 2023). "Our study also discovered a number of candidate therapeutic targets for the treatment of B cell neoplasms, including NF-κB2, PKCδ, MCC, PARP1, and PHB2." (PMID 25960828, 2015). "Since our new proteomic data identified PARP1 and PHB2/PHB1 as two signaling hubs of the novel oncoprotein MCC in human MM cells, we are currently testing the therapeutic efficacy of PARP1 inhibitors and PHB ligands in B cell neoplasms with TRAF3 inactivation or aberrant MCC expression." (PMID 25960828, 2015). "Furthermore, the central role of PARP1 and PHB2 in the MCC interaction network of human MM cells implies that PARP1 inhibitors and PHB ligands may have therapeutic application in B cell neoplasms, including NHL and MM." (PMID 25200342, 2014).
Burkitt lymphoma (3 papers, 2017 to 2018). A rare form of malignant mature B-cell non-Hodgkin lymphoma. "Therefore, to identify targets of LMP1 that are regulated through PARP1, LMP1 was ectopically expressed in an EBV-negative Burkitt’s lymphoma cell line." (PMID 30395643, 2018). "Moreover, conditional RNAi-mediated depletion of CHK1 in BL2 Burkitt lymphoma and Nalm6 pre-B ALL cells coincided with the induction of apoptosis, as indicated by PARP1 cleavage, a marker of caspase activation." (PMID 29167438, 2017).
cerebellar degeneration (3 papers, 2013 to 2017). Degeneration of the cerebellum. "We next investigated the requirement for Parp1 in MMS-induced cerebellar degeneration." (PMID 23593019, 2013). "Parp1 gene deletion completely rescued MMS-induced cerebellar degeneration in both the WT and AagTg backgrounds, regardless of gender." (PMID 28978150, 2017). "We found that Parp1 gene deletion resulted in complete protection against MMS-induced retinal and cerebellar degeneration in both WT and AagTg mice, regardless of gender." (PMID 28978150, 2017).
cerebral infarction (3 papers, 2021 to 2025). An ischemic condition of the brain, producing a persistent focal neurological deficit in the area of distribution of the cerebral arteries. "APG treatment has improved the volume of cerebral infarction and neurological deficits, reduced brain edema, and decreased parthanatos and apoptosis by inhibiting PARP1/AIF pathway." (PMID 38746012, 2024). "PARP-1 inhibition decreased brain infarction and neutrophil infiltration after transient focal cerebral ischemia and can protect against traumatic injury and decrease nitric oxide production." (PMID 33671196, 2021).
chronic heart failure (3 papers, 2022 to 2025). "The role of PARP inhibitors for the treatment of oncological diseases has been investigated and it has been reported that PARP‐1 inhibitors may be efficacious in the management of myocardial infarction, cardiopulmonary bypass, and chronic heart failure." (PMID 40703196, 2025). "Patients with chronic heart failure (CHF) and volunteers with a normal heart function are investigated for examining oxidative stress-related activation of PARP1." (PMID 35806303, 2022).
chronic kidney disease (3 papers, 2010 to 2019). Impairment of the renal function secondary to chronic kidney damage persisting for three or more months. "In addition, the level of 2PY, an end product of NAD degradation, increases in the serum of chronic renal failure patients, and is associated with the deterioration of kidney function and toxicities including significant PARP-1 inhibition." (PMID 29348849, 2017). "2PY levels are elevated in chronic kidney disease patients where it may act as a uremic toxin by inhibiting poly (ADP-ribose) polymerase-1 (PARP-1)." (PMID 31281289, 2019).
cognitive decline (3 papers, 2024 to 2026). "Impaired DNA repair mechanisms, such as those involving BRCA-2 and PARP-1, exacerbate neuronal damage and cognitive decline." (PMID 40282301, 2025).
colorectal adenocarcinoma (3 papers, 2014 to 2025). The most common type of colorectal carcinoma. "We additionally analyzed MNNG- and TNF-induced activation/disappearance of PARP-1, depletion of intracellular ATP and loss of membrane integrity in human leukemic Jurkat T cells and human HT-29 colorectal adenocarcinoma cells as two additional established cell systems for necroptosis." (PMID 23760205, 2014).
Crohn disease (3 papers, 2023 to 2025). A gastrointestinal disorder characterized by chronic inflammation involving all layers of the intestinal wall, noncaseating granulomas affecting the intestinal wall and regional lymph nodes, and transmural fibrosis. "A few years later, autoantibodies against PARP1 (zinc-finger motifs F1 and F2) were identified in Crohn’s disease patients and the level of the specific autoantibody showed a correlation with the Crohn’s disease activity index (CDAI)." (PMID 37457706, 2023). "In comparison to PARP1, the highest catalytic activity member of ADPRT enzyme superfamily, whose role was widely investigated in Crohn’s disease, PARP2 was rarely investigated." (PMID 37457706, 2023).
dementia (3 papers, 2016 to 2022). Loss of intellectual abilities interfering with an individual's social and occupational functions. "We compared the gene expression of APE1, OGG1, Polβ and PARP1 in 41 AD patient with dementia, 28 patients with MCI due to AD pathology, 45 patients with MCI and 24 patients with SCI and 28 HC." (PMID 27234294, 2016). "However, this is the first report to observe evidence of PARP1 activation in the cortex regions from postmortem PD (with dementia) patients brains." (PMID 29290984, 2017).
diffuse intrinsic pontine glioma (3 papers, 2011 to 2022). A neuroglial tumor that arises from the middle portion of the brain stem. "Recently, low-level gains in PARP1 were identified in a subset of patients suffering from diffuse intrinsic pontine glioma (DIPG), using a whole-genome single nucleotide polymorphism (SNP) – based microarray." (PMID 22184287, 2011).
dyslexia (3 papers, 2018 to 2024). A learning disorder characterized by an impairment in processing written words. "Interestingly, PARP1 is one of the genes that are differentially expressed among (mammalian) vocal learners, and its product regulates as well the dyslexia-susceptibility gene DYX1C1, important for neuronal migration in the developing cortex." (PMID 29922639, 2018). "The number of chemicals involved in dyslexia-related genes ranged from 1 to 532 (PARP1)." (PMID 39020327, 2024).
ependymoma (3 papers, 2011 to 2019). A WHO grade II, slow growing tumor of children and young adults, usually located intraventricularly. "In tissue sections derived from ependymoma patients a similar tendency towards strong and abundant nuclear PARP1 staining was observed: in 16 out of 18 sections a convincing nuclear PARP1 staining was found in at least 30% of tumor cells." (PMID 22184287, 2011).
experimental autoimmune encephalomyelitis (3 papers, 2022 to 2025). An autoimmune demyelinating disease of the central nervous system that is produced experimentally in animals by the injection of homogenized brain or spinal cord in Freund's adjuvant. "However, significant PARP1 activity was found in plaque regions of the brain of marmoset monkeys with experimental autoimmune encephalomyelitis (EAE), and PARP1 activity was significantly increased in the astrocytes, microglia, endothelial cells, oligodendrocytes, and neurons surrounding the plaque." (PMID 36438061, 2022).
HCMV infection (3 papers, 2017 to 2024). "Moreover, our results showed that PARP-1 depletion caused more severe defects in HCMV infection than PARP-1 inhibition." (PMID 36146855, 2022). "The role of UL76 on PARP1 and PARylation should be examined in cell lines which are permissive for HCMV infection." (PMID 36146855, 2022). "We initially employed Olaparib (PARPi) and pDD00017273 (PARGi), small molecular inhibitors against PARP-1 and PARG, respectively, to investigate the role of PARP-1 and protein PARylation on HCMV infection." (PMID 36146855, 2022). "We hypothesized that, during HCMV infection, viral DNA replication results in DNA nicks or gaps, which induces PARP-1 activation." (PMID 36146855, 2022). "As HCMV infection activated PARP-1 and induced the reposition of PARP-1, we want to know whether HCMV infection also affected the expression of PARG." (PMID 36146855, 2022). "HCMV infection only caused a moderate decline in cell NAD+ levels, implying that PARP-1 activation may be tightly regulated to prevent its over-activation and dramatic NAD+ decrease after HCMV infection." (PMID 36146855, 2022). "Whether UL76 affect the translocation of PARP1 induced by HCMV infection also need to be investigated." (PMID 36146855, 2022). "The increased IFN genes transcription may contribute to the inhibitory effect of PARP-1 inhibition or depletion on HCMV infection." (PMID 36146855, 2022). "We also found that PARP-1 was translocated from nucleus to cytoplasm upon HCMV infection." (PMID 36146855, 2022). "We first examined whether HCMV infection activates PARP-1 in fibroblasts." (PMID 36146855, 2022). "Thus, the activation of PARP-1 upon HCMV infection may result from ROS-induced host’s DNA damage or nicks and breaks on the incoming viral genome." (PMID 36146855, 2022). "The role of PARP-1 and protein PARylation in HCMV infection is still unknown." (PMID 36146855, 2022). "However, HCMV infection induced the translocation of PARP-1 from the nucleus to cytoplasm." (PMID 36146855, 2022). "HCMV infection triggered the activation of PARP-1 and induced the translocation of PARP-1 from nucleus to cytoplasm." (PMID 36146855, 2022). "However, the effect of HCMV infection on the activation of PARP-1 is still unknown." (PMID 36146855, 2022). "PARP-1 is potently activated by DNA damage and facilitates DNA repair, and it has been well documented that both HSV-1 and HCMV infection activate certain DNA damage responses." (PMID 36146855, 2022). "Collectively, we explored the role of PARP-1 and PARG in HCMV infection and uncovered the relationship between HCMV and protein PARylation." (PMID 36146855, 2022). "In the present study, we explored the role of PARP-1 in HCMV infection and found that HCMV infection activated PARP-1 and increased protein PARylation as early as 12 hpi." (PMID 36146855, 2022). "Given that HCMV infection resulted in PARP-1 activation, the “true late” protein UL76 may prevent the overactivation of PARP-1 during HCMV infection, which may avoid the dramatic change in NAD+ levels." (PMID 36146855, 2022). "During HCMV infection, PARP-1 may be continuously activated, and the activated PARP-1 produced a large amount of PAR polymers which could serve as a death signal to the host cells." (PMID 36146855, 2022). "PARP-1 depletion also elevated IFN-β and ISG15 transcription upon HCMV infection." (PMID 36146855, 2022). "This indicated that the important role of PARP-1 on HCMV infection might not be limited to PARP-1-mediated antiviral immunity." (PMID 36146855, 2022). "In the present study, we investigated the role of PARP-1 and PARG on HCMV infection and identified HCMV UL76 as a novel regulator of PARP-1 activity." (PMID 36146855, 2022). "As PARP1/2 are major consumers of NAD+, these findings may suggest that these enzymes are not activated and that PAR is less abundant throughout HCMV infection." (PMID 28507315, 2017).
HCMV infection (continued). "Interestingly, UL24 and ORF20, two UL76 homologs from HSV-1 or KSHV, respectively, could not bind with PARP-1 and PAR chains, indicating that this unique regulation of protein PARylation was specific to HCMV infection." (PMID 36146855, 2022).
hepatoblastoma (3 papers, 2018 to 2024). Hepatoblastoma (HB) is a malignant hepatic tumor and is the most common pediatric liver cancer. "To confirm our results in HepG2 cells, we further examined the effects of PARP1 inhibition by DPQ treatment on the PARP1/Ku80/Ku70 complexes and TSPs in another hepatoblastoma cell line, Huh6." (PMID 30271949, 2018). "We next examined proliferation of three hepatoblastoma-derived cell lines, HepG2, Huh6, and B6-2, in which PARP1 was inhibited by si-PARP1." (PMID 30271949, 2018). "Studies have shown that activation of PARP-1 may lead to post-translational modifications of tumor suppressor genes along with activation of WNT/β-catenin signaling to induce the development of hepatoblastoma." (PMID 31511432, 2019). "Therefore, we next examined if DPQ-mediated inhibition of PARP1/Ku80/Ku70 complexes and subsequent repression of the ALCDs in hepatoblastoma cells might inhibit cell proliferation." (PMID 30271949, 2018). "There have been other molecules that participate in Wnt/β-catenin triggered signaling pathway in hepatoblastoma including tumor necrosis factor-α (TNF-α), regenerating islet-derived 1 and 3 α (REG1A and 3A), substance P (SP)/neurokinin-1 receptor and PARP-1." (PMID 31511432, 2019). "Furthermore, inhibition of PARP1 by low doses of two inhibitors, DPQ and olaparib, blocks activation of TSPs and cancer-related genes in hepatoblastoma cell lines, HepG2, Huh6, and B6-2, which facilitates the development of clinical trials for patients with aggressive HBL." (PMID 30271949, 2018).
Hypercholesterolemia (3 papers, 2020 to 2024). An increased concentration of cholesterol in the blood. "Intriguingly, despite PKO mice manifesting increased hepatic cholesterol accumulation, their hypercholesterolemia was ameliorated, implying that the regulation of whole body cholesterol homeostasis by PARP1 is considerably more complicated than the current model." (PMID 33061802, 2020).
inflammatory bowel disease (3 papers, 2019 to 2025). A spectrum of small and large bowel inflammatory diseases of unknown etiology. "PARP-1 is also involved in acute and chronic inflammatory bowel disease (IBD), as in the inflamed colon it induces cell death, activates NF-κB and AP-1, and sustains inflammatory cytokine production." (PMID 31877876, 2019). "Interestingly, in inflammatory bowel disease, beneficial effects were obtained with both PARP and PARG inhibitors, the latter compromising PAR degradation and thus sustaining PARP-1 auto-inhibition." (PMID 31877876, 2019).
Insulin resistance (3 papers, 2013 to 2023). Increased resistance towards insulin, that is, diminished effectiveness of insulin in reducing blood glucose levels. "A role of PARP1 in glucose metabolism is also suggested by Parp1-knockout mice that are more susceptible to diet-induced insulin resistance and glucose intolerance compared with WT mice." (PMID 32443613, 2020). "Treatment with PARP inhibitors or deletion of PARP1 in mice fed a high-fat diet increased NAD+ levels, improved SIRT1 activity and rescued mitochondrial function, thereby protecting the obese mice from insulin resistance." (PMID 37165408, 2023).
invasive ductal carcinoma (3 papers, 2015 to 2020). "Within breast infiltrating ductal carcinoma samples tested, mean PARP1 expression was significantly higher compared to normal breast tissue." (PMID 32423430, 2020). "Furthermore, tissue arrays of 183 breast invasive ductal carcinoma and 10 adjacent normal tissue specimens were examined by IHC with anti‐KLF4 and anti‐PARP1, and visualized by DAB staining." (PMID 33231937, 2020).
kidney injury (3 papers, 2013 to 2022). Trauma to the kidney. "Studies by Kim demonstrated that the provision of spermidine in the drinking water reduced the severity of I/R-induced kidney injury in mice through the inhibition of DNA nitration and modulation of poly (ADP-ribose) polymerase 1 (PARP1) activity." (PMID 31561575, 2019).
latent infection (3 papers, 2021 to 2024). "In addition to maintaining latent infection, PARP1 activity has been implicated in regulating the lytic EBV cycle through similar methods." (PMID 38392869, 2024). "In addition to regulating KSHV latent infection, PARP1 is responsible for enabling the replication of KSHV during latent infection." (PMID 38392869, 2024). "PARP1 is involved in the regulation of EBV latent infection." (PMID 35095818, 2021). "PARP1 has been shown to bind to KSHV’s terminal repeat sequence (which, during latent infection, functions as an origin of replication) and PARylate the latency-associated nuclear antigen associated with the terminal repeat sequence during latent infection." (PMID 38392869, 2024).